PML (PML nuclear body scaffold)
Diseases named in the same sentence as PML in open-access papers (continued):
Sharing a sentence is not in itself a finding about the gene and the disease.
HCMV infection (continued). "Since HCMV IE1 inhibits the activation of ISRE-containing promoters by sequestering STAT2 and PML, IE1 expression may be responsible for the suppression of free ISG15 and ISG15 conjugate levels during HCMV infection." (PMID 27564865, 2016). "During HCMV infection, viral IE1 protein interacted with PML, STAT1, STAT2, and HDACs." (PMID 25812002, 2015). "Moreover, four proteins, promyelocytic leukemia protein (PML), hDaxx, Sp100, and viperin, have been identified as restriction factors that mediate intrinsic immunity against HCMV infection." (PMID 22701276, 2012). "However, PML is not degraded during HCMV infection, but the ND10 bodies are dispersed in an IE1-dependent manner." (PMID 33546431, 2021). "However, no direct evidence for a role for PML was shown and it is interesting to note that in HCMV infection of non-permissive THP1 cells the presence or absence of PML has been reported to have no impact on the establishment of latent infections." (PMID 29547547, 2018). "However, PML does not seem to control this HDAC activity during HCMV infection, since PML knockdown did not significantly affect IRF3 phosphorylation after UV-HCMV infection." (PMID 25812002, 2015). "Since several interaction partners of Daxx, including ATRX, have been shown to bind in a mutually exclusive manner, the absence of ATRX from PML cages may indicate an altered regulation of Daxx during HCMV infection that leads to a switch of interaction partners." (PMID 35319461, 2022). "In summary, these data show that PML-NBs, when not disrupted by IE1, undergo a drastic redistribution during HCMV infection." (PMID 35319461, 2022). "Collectively, after HCMV infection, SCM-specific SUMOylation confers UL44 protein co-localization with the PML component of ND10 compartments, which is not the indirect recruitment by PIAS3." (PMID 34747321, 2021). "These negative effects of Daxx on HCMV infections were quickly confirmed and extended to the additional PML-NB proteins ATRX, BclAF1, PML, and Sp100 by multiple independent groups." (PMID 32226778, 2020).
prostate carcinoma (23 papers, 2010 to 2024). A carcinoma that arises from epithelial cells of the prostate gland. "The oncogenic role of E6AP in prostate cancer is also associated with ubiquitin-dependent degradation of the tumor suppressor proteins PML and p27Kip1, which is characteristic in aggressive and late stages of prostate cancer." (PMID 32751183, 2020). "In certain types of tumors, such as prostate cancer, PML loss correlates with invasive and metastatic progression." (PMID 22935031, 2012). "These clinical data strongly suggest the existence of this PML destruction pathway in prostate cancer and the association of its hyperactivation with disease progression." (PMID 22935031, 2012). "Interestingly, PML is frequently co-deleted with PTEN in metastatic prostate cancer, suggesting that PML loss could modulate PGC-1α in prostate cancer through SIRT1." (PMID 29629336, 2018). "PML, a proto-oncogene, was downregulated in prostate cancer, leading to the downregulation of the cell surface HLA class I molecule and immune escape." (PMID 35216190, 2022). "A study that examined knockdown of E6AP in both prostate cancer cell line and xenogrfts, showed that its down regulation resulted in PML accumulation, triggered efficient cellular senescence and lead to attenuation of tumor cells growth." (PMID 28966805, 2017). "These clinical findings support the significance of KLHL20/PML pathway in the progression of prostate cancer and suggest a promise for targeting this pathway in the treatment of aggressive prostate cancers." (PMID 27042198, 2016). "KLHL20 is induced by HIF-1α protein and forms a KLHL20-cullin 3 complex that degrades the promyelocytic leukemia protein (PML) leading to prostate cancer progression." (PMID 23676014, 2013). "Clinically, overexpression of HIF-1α, KLHL20, Pin1 and downregulation of PML are found in prostate cancers." (PMID 22935031, 2012). "In addition, a connection between CK2 and FOXO3a via Promyelocytic leukemia protein (PML) has been found in human prostate cancer." (PMID 36009534, 2022). "Pin1 promotes E3 ligase KLHL20-mediated degradation of PML to enhance prostate cancer progression." (PMID 33807199, 2021). "Subsequently, we found the effects of PML-induced LC3 recruitment within PML NBs occurred in several human cell lines tested, including human cervical cancer cell line HeLa, laryngeal carcinoma cell line Hep2, prostate cancer cell line PC3, HEK293T and neuroblastoma cells SK-N-SH." (PMID 25419843, 2014). "It would be intriguing to test whether MLN4924 attenuates prostate cancer progression induced by KLHL20-mediated PML degradation." (PMID 22935031, 2012). "Pin1 reverses the inhibitory mechanism of PML-mediated suppression of HIF-1α-induced angiogenesis in clear cell renal cell carcinoma and prostate cancer." (PMID 33807199, 2021). "Under hypoxic conditions, the hypoxia transcription factor HIF1α upregulates KLHL20, an E3 subunit, which promotes degradation of PML in a CDK2- and Pin1-dependent manner, thus promoting prostate cancer progression." (PMID 29416846, 2018). "In human prostate cancer, high expression of HIF-1α, KLHL20, and Pin1 is frequent observed and correlates with PML low expression." (PMID 27042198, 2016). "Under hypoxic conditions, HIF-1 pathways upregulate the BTB protein KLHL20, and the Cullin3-KLHL20 E3-ligase targets the PML protein for degradation to potentiate HIF-1 signalling and disease progression in prostate cancer." (PMID 26544623, 2015). "As a negative control, prostate cancer PC3 cells represented a tumor type where PML is downregulated." (PMID 38730056, 2024). "However, most of the evidence for PML bodies role in cancer relates to the PML protein, not SP100, which has not been implicated in prostate cancer." (PMID 31681438, 2019).
chronic myeloid leukemia (22 papers, 2009 to 2025). "In the first paper, PML was described as an essential regulator of stem cell maintenance, both in normal hematopoiesis and in chronic myeloid leukemia, as deletion of Pml in KO mice led to loss of quiescence and exhaustion of hematopoietic and leukemia stem cells." (PMID 24575390, 2014). "Table A1 also highlights specific rearrangements and mutations linked to SEs in different cancers; for instance, gene fusions like BCR-ABL1 and PML-RARA are often seen in chronic myeloid leukaemia (CML) and acute promyelocytic leukaemia (APL), respectively." (PMID 38542080, 2024). "Paradoxically, PML exerts a prosurvival role conferring a selective advantage in chronic myeloid leukemia and specific solid tumors." (PMID 31570853, 2020). "Depletion of PML impairs the self-renewal activity in the leukemic stem cell from chronic myeloid leukemia." (PMID 31570853, 2020). "Overall, these studies are in agreement with PML’s widely reported function as a tumour suppressor in a variety of both haematopoietic and solid tumours, however, chronic myeloid leukaemia (CML) is an exception to this." (PMID 29110249, 2018). "In line with the two opposing activities of PML shown in chronic myelocytic leukemia and triple-negative breast carcinoma cells, we also found a dual role for PML in HBsAg-related pathogenesis." (PMID 27058621, 2016). "The tumor suppressor promyelocytic leukemia protein (PML) has been demonstrated to play a critical role in the maintenance of quiescent chronic myeloid leukemia (CML) stem cells." (PMID 26273420, 2015). "Similarly, high PML expression in chronic myeloid leukemia maintains hematopoietic stem cells and PML ablation leads to an increase in their initial cycling activity that eventually leads to their eradication." (PMID 37518985, 2023). "The chromosome 9 and 22 translocations in chronic myelogenous leukemia (CML) produce the PML-RARα gene; similar chromosomal translocations in tumors are reported to produce fusion-circular RNAs (f-circRNAs) and facilitate the progression of diseases such as leukemia." (PMID 35795049, 2022). "Indeed, although many studies have documented loss of expression of PML in tumors of different histological origin, more recently high expression of PML has been reported in triple-negative breast cancer and chronic myeloid leukemia." (PMID 24575390, 2014). "Autophagy is a critical mechanism of the anti-leukemic effects of ATO and contributes to the ATO-induced degradation of fusion oncoproteins such as PML-RARA in APL cells and BCR-ABL in chronic myelocytic leukemia (CML) cells 8-11." (PMID 32284743, 2020).
lung carcinoma (22 papers, 2010 to 2025). "Loss of PML has been correlated with poor clinical outcome in a variety of human cancers, including lung cancer, supporting its tumor suppressor function." (PMID 20625391, 2010). "To further reveal the role of each distinct PML isoform in HAdV regulation, we stably transduced human hepatocellular carcinoma (HepG2) and human lung carcinoma (H1299) cells with a lentiviral vector encoding PML specific shRNA sequence for efficient depletion of all endogenous PML isoforms." (PMID 35699431, 2022). "CK2α was reported to phosphorylate PML at Ser 517 and promote its ubiquitination-mediated degradation, thereby promoting tumorigenesis and development of lung cancer." (PMID 39827153, 2025). "WDR4 can also act as an adaptor and mediate the ubiquitination-mediated degradation of the tumor suppressor gene PML, thus promoting the progression of lung cancer." (PMID 37783676, 2023). "WDR4 is highly expressed in lung cancer and promotes lung cancer progression and metastasis by targeting PML tumor suppressor for ubiquitination." (PMID 37821451, 2023). "For lung carcinoma H1299 cells, we only observed moderate PML isoform-specific changes of E1B-55K levels." (PMID 35699431, 2022). "In contrast, in this study comprehensive analysis was performed in stably transduced human hepatocellular or lung carcinoma cell lines expressing PML proteins." (PMID 35699431, 2022). "A recent study also reported that ubiquitination of PML promotes lung cancer progression via fostering immunosuppression in the tumor microenvironment." (PMID 36439512, 2022). "In subsequent studies, engineered repression of USP18/UBP43 (ISG15 deconjugating enzyme) was shown to destabilize PML-RARα, reduce proliferation, and increase apoptosis in acute promyelocytic leukemia and lung cancer cell lines." (PMID 35159348, 2022). "Since the strongest correlation between DDIT4 and PML expression occurred in lung cancer derived cell lines, and specifically lung adenocarcinoma (Spearman’s 0.399, p < 0.01), we extended our analysis to lung cancer subtypes." (PMID 28332630, 2017). "While higher PML expression‏ in invasive and proliferative cells of liver carcinoma in‏ contrast to lower PML expression in proliferative cells‏ of lung cancer has been reported." (PMID 28959333, 2016). "Knockdown of the CSNK2A1P gene expression with specific siRNA increased the PML protein level in lung cancer cells." (PMID 20625391, 2010). "We demonstrated the correlation between CSNK2A1P gene and PML protein stability in only two lung cancer cell lines in vitro." (PMID 20625391, 2010). "To determine the potential mechanism by which the 398T allele is preferentially amplified in lung cancer samples, we studied the effects of the two alleles of the CSNK2A1P gene on tumor suppressor PML protein." (PMID 20625391, 2010). "For instance, CK2 promotes PML degradation and CK2 kinase activity is inversely correlated with PML protein levels in human lung cancer." (PMID 20625391, 2010). "Furthermore, Wang and colleagues noted that the aberrant expression and release of SAA2 regulated by WDR4/PML promotes lung cancer progression by increasing intertumoral Tregs and M2-like macrophages while reducing CD8+ T cell infiltration." (PMID 39457484, 2024). "In addition, WDR4 can act as a ubiquitinated substrate adaptor molecule and mediate the degradation of PML by ubiquitination to promote lung cancer progression." (PMID 37783676, 2023). "CK2 regulates ubiquitin-mediated degradation of PML in human lung cancer cell lines." (PMID 20625391, 2010). "Furthermore, WDR4 negatively regulates PML expression to enhance lung cancer development by creating a pro-metastatic and immunosuppressive status, which may be helpful for potential future treatments in lung cancer patients." (PMID 39440054, 2024). "Since GATA4 induces lung cancer cell senescence through downregulating WNT7B, we checked PML-HIRA colocalization signal triggered by ectopic expression of GATA4." (PMID 30971692, 2019).
lung carcinoma (continued). "We also assessed PML and DDIT4 mRNA expression correlations by cancer cell tissue type and found significant (p < 0.05) and strong correlations (Spearman’s r = 0.275–0.345) in breast, ovarian and lung cancer cells." (PMID 28332630, 2017). "Finally, we found that PIAS1 and PML expression are inversely correlated in NSCLC cell lines and in primary lung cancers and prostate (Rabellino and Scaglioni, unpublished data)." (PMID 23526763, 2013). "Finally, it has been shown an inverse correlation between the level of PML proteins and CK2 kinase activity in human lung cancer specimens." (PMID 23526763, 2013). "To further address the question of whether the CSNK2A1P mRNA is fully translated and degrades PML in cancer cells, we knocked down the CSNK2A1P gene in H1299 lung cancer cell lines with siRNA specific to the CSNK2A1P gene." (PMID 20625391, 2010). "Interestingly, we found that GATA4 expression resulted in similar level of PML-HIRA colocalization to that found in WNT7B knockdown, suggesting that mechanism revealed by Adams and colleagues may apply to GATA4 induced senescence in lung cancer cells." (PMID 30971692, 2019).
glioma (17 papers, 2013 to 2026). A benign or malignant brain and spinal cord tumor that arises from glial cells (astrocytes, oligodendrocytes, ependymal cells). "SMARCAL1 localizes to ALT-associated PML (Promyelocytic leukemia protein) bodies in ALT-positive glioma cell lines, including IDH-mutant astrocytomas." (PMID 41520142, 2026). "The loss of PML-NBs is an H3.3-specific phenomenon and suggests that PML disruptions can contribute to oncogenesis in H3.3-mutated pediatric gliomas." (PMID 38066546, 2023). "We find that the pediatric glioma-associated H3.3 point mutations disrupt the formation of PML nuclear bodies and this prevents differentiation down glial lineages." (PMID 38066546, 2023). "We find that IDH1 R132H point mutations also disrupt PML-NBs, suggesting that defective PML-NBs are a common oncogenic driver in gliomas and myeloid leukemias." (PMID 38066546, 2023). "We have demonstrated that H3.3 mutations disrupt PML-NBs in pediatric gliomas and contribute to oncogenesis." (PMID 38066546, 2023). "We also find that point mutations in IDH1/2—which are common events in adult gliomas and myeloid leukemias—also disrupt the formation of PML bodies." (PMID 38066546, 2023). "Consistent with this, histone-mutated gliomas are also highly sensitive to treatment with arsenic trioxide, which targets PML-NBs, showing that this pathway can be targeted for therapy." (PMID 38066546, 2023). "We now find that the IDH1 R132H mutation also disrupts the formation of PML-NBs in pediatric gliomas." (PMID 38066546, 2023). "In particular, contradicting evidence showed growth inhibition of glioma cells by PM I overexpression or an increase in tumor cell growth by PML loss in murine NPC-derived gliomas." (PMID 34208139, 2021). "The therapeutic potential of As2O3 on glioma is partially attributed to PML degradation which consequently leads to the PML-associated C-Myc degradation." (PMID 29416846, 2018). "Taken together, these results strongly suggest that the PML pathway is a major contributor to oncogenesis in histone-mutated pediatric gliomas, and this pathway could represent a novel therapeutic target." (PMID 38066546, 2023). "Given the strong association between ATRX/H3.3 and PML-NBs, we sought to determine if pediatric glioma H3.3 mutations might exert oncogenic effects through disruption of PML-NBs, as is the case in APL." (PMID 38066546, 2023). "Strikingly, H3.3-mutated gliomas exhibit a very similar phenotype of stalled differentiation, indicating H3.3 mutations may affect PML-NBs." (PMID 38066546, 2023). "We found that glioma cells treated with ATO behaved similarly to PML-RARα mutated APL." (PMID 38066546, 2023). "Our findings suggested that SOX2 promotes HCMV gene expression and replication in gliomas by downregulating PML." (PMID 37058447, 2023). "Due to the SOX2-mediated downregulation of PML and Sp100, the PML-NBs formation is greatly reduced in glioma cells, removing the restriction on HCMV gene expression." (PMID 37058447, 2023). "To test this, we first assessed the effects of ATO treatment on PML protein expression in pediatric glioma cell lines." (PMID 38066546, 2023). "To confirm this antiviral activity in glioma cells, we examined the effects of PML-KO and OE in U251 and U87 cells infected with HCMV." (PMID 37058447, 2023). "Similar suppression of viral gene expression was observed in glioma cells with elevated PML or Sp100 levels in this study." (PMID 37058447, 2023). "We find that H3.3 point mutations interfere with the formation of PML-NBs and, much like APL, these PML defects contribute to blocked differentiation in pediatric gliomas." (PMID 38066546, 2023). "We identify PML as a contributor to oncogenesis in a subset of gliomas and show that targeting PML bodies is effective in treating these H3.3-mutated pediatric gliomas." (PMID 38066546, 2023).